TLR9 (toll like receptor 9)
Diseases named in the same sentence as TLR9 in open-access papers (continued):
Sharing a sentence is not in itself a finding about the gene and the disease.
abortion (3 papers, 2018 to 2026). the ending of pregnancy by removing a fetus or embryo before it can survive outside the uterus. "Our study provides the first evidence that the inhibition of TLR9 activity at the time of conception in abortion-prone mice is also detrimental." (PMID 41596497, 2026). "TLR9 and IL-10 SNPs have been found to play critical roles in the development of spontaneous abortion." (PMID 30116270, 2018). "We have included three important and different in function Toll-like receptors (TLR2, TLR4, and TLR9) to study the relation between TLR SNPs and risk of spontaneous abortion." (PMID 30116270, 2018). "TLR9 is strongly expressed in the decidua of spontaneous abortion compared to normal human pregnancies, making it possible that targeted inflammatory stimuli to the reproductive tract might elicit an inflammatory response leading to PTB." (PMID 29269517, 2018). "Based on these findings, the aim of this study was to determine whether inhibition of TLR9 by the antagonist ODN 2088, administered immediately after mating, improves pregnancy outcomes in an abortion-prone murine model." (PMID 41596497, 2026). "Therefore, this study aimed to determine whether inhibition of TLR9 activity via administering the antagonist ODN 2088 at the time of conception could modulate immune regulation and improve pregnancy outcomes in the murine abortion-prone model CBA/J × DBA/2J." (PMID 41596497, 2026). "Blocking TLR9 signaling shortly after mating in the CBA/J × DBA/2J, abortion-prone model did not improve pregnancy outcomes but rather exacerbated pregnancy loss without affecting implantation success." (PMID 41596497, 2026). "Furthermore, we observed that ODN 2088 administration did not significantly affect the number of implantation sites, suggesting that early TLR9 signaling in the considered abortion-prone murine model may not play a critical role in blastocyst attachment or endometrial receptivity." (PMID 41596497, 2026).
acute GVHD (3 papers, 2011 to 2016). "Donor TLR9 gene tag single nucleotide polymorphisms (SNPs), +1174A/G (rs352139) and +1635 C/T (rs 352140), respectively, correlated increased severity of acute GVHD and CMV reactivation." (PMID 27965667, 2016). "Two other SNPs in the TLR9 gene in the donor, 1174G/A and 1635C/T (rs352140), influenced the risk of both acute graft-versus-host disease and HCMV reactivation in allogeneic hematopoietic recipients." (PMID 27105145, 2016). "Furthermore, investigators have reported that TLR2 stimulation can induce Th2 immunity, which is the prominent immunity of chronic GVHD, whereas TLR9 stimulation promotes Th1 immune responses, the characterized immunity of acute GVHD." (PMID 22025895, 2011).
acute respiratory distress syndrome (3 papers, 2022 to 2025). Progressive and life-threatening pulmonary distress in the absence of an underlying pulmonary condition, usually following major trauma or surgery. "In support of this idea, a study reported that in a model of acute respiratory distress syndrome (ARDS), induced by the STING agonist diABZI, TLR9 contributes to neutrophils recruitment." (PMID 37187738, 2023).
AIDS (3 papers, 2013 to 2022). A syndrome resulting from the acquired deficiency of cellular immunity caused by the human immunodeficiency virus (HIV). "The SNPs within the TLR2, TLR4, and TLR9 genes that may contribute to an increased susceptibility of AIDS patients to TM were checked by the time of flight mass spectrometry (TOF/MS) method." (PMID 33777838, 2021). "In total, 23 SNPs in the TLR2, TLR4, and TLR9 genes, which may influence the susceptibility of AIDS patients to TM, were checked by the time of flight mass spectrometry (TOF/MS) method among these Han Chinese subjects." (PMID 33777838, 2021). "Furthermore, the polymorphism of TLR7 and TLR9 SNPs are associated with HIV susceptibility, and some mutations may delay the development of AIDS in ECs or LTNPs." (PMID 35211115, 2022). "Among the study subjects, the susceptibility of AIDS patients to TM seems to be independent of the selected TLR2, TLR4, and TLR9 polymorphisms." (PMID 33777838, 2021).
brain injury (3 papers, 2017 to 2023). Acute and chronic (see also brain INJURIES, CHRONIC) injuries to the brain, including the cerebral hemispheres, CEREBELLUM, and brain STEM. "Other possible situations, which may sensitize microglial TLR9 pathway, include CNS and systemic infections as well as brain trauma." (PMID 29934589, 2018). "Sevoflurane pretreatment can activate TLR3 and TLR9 signaling pathway, upregulate TLR3 expression and TRIF expression, decrease TLR9 expression, and downregulate NF-κB expression and inhibited the production of S100β and IL-6, thereby lessening CPB inflammation-induced brain injury." (PMID 29445737, 2017).
cardiac hypertrophy (3 papers, 2015 to 2020). "CpG-ODN, classic agonists of TLR9, have also been found to attenuate pathological cardiac hypertrophy and HF by activating PI3K/AKT41." (PMID 32029708, 2020). "A similar study showed another synthetic agonist of TLR9 that activated the phosphoinositide 3-kinase/protein kinase B signaling pathway and attenuated pathological cardiac hypertrophy and HF." (PMID 29576748, 2018). "A previous study by Takafumi Oka reported that TLR9 ablation could protect against cardiac hypertrophy and HF39." (PMID 32029708, 2020). "In summary, mCRAMP protected against pressure overload-induced cardiac hypertrophy by activating both the IGFR1/PI3K/AKT and TLR9/AMPKa pathways in cardiomyocytes." (PMID 32029708, 2020).
cervicitis (3 papers, 2018 to 2023). An acute or chronic inflammatory process that affects the cervix. "With regard to TLR9 gene polymorphisms, we found promoter rs187084 TC genotype to be associated with an increased risk of cervicitis." (PMID 31365550, 2019). "Based on our results, we suggest a significant influence of TLR4 and TLR9 polymorphisms on cervicitis." (PMID 31365550, 2019). "The TLR4 and TLR9 SNPs as well as haplotypes modulated the cervicitis risk as a whole and TV induced cervicitis as well." (PMID 31365550, 2019). "Genotype and allele frequency distribution of TLR4 and TLR9 gene polymorphisms in cervicitis and control subjects." (PMID 31365550, 2019). "Ten single nucleotide polymorphisms, five each of TLR4 and TLR9 genes were analyzed among 130 cervicitis patients and 150 controls either using polymerase chain reaction-restriction fragment length polymorphism or allele specific-PCR." (PMID 31365550, 2019). "TLR4 and TLR9 polymorphisms, as well as haplotypes were shown to modulate the cervicitis risk." (PMID 31365550, 2019). "TLR4 haplotype GCA and TLR9 haplotype GTA were associated with a lower and higher risk of cervicitis." (PMID 37937275, 2023). "The rs11536889 CC (TLR4) and rs187084 TC (TLR9) genotypes had a larger distribution in cervicitis patients than in controls." (PMID 37937275, 2023). "TLR4 rs11536889 CC (age-adjusted OR, 2.469 [95% CI, 1.499 to 4.065]; p < 0.001) and TLR9 rs187084 TC (age-adjusted OR, 2.165 [95% CI, 1.267–3.699]; p = 0.005) genotypes showed the higher distribution in cervicitis patients compared to controls." (PMID 31365550, 2019). "The TLR4 haplotype GCA (OR, 0.6 [95% CI, 0.38–0.95]; p = 0.0272) and TLR9 haplotype GTA (OR, 1.99 [95% CI, 1.14–3.48]; p = 0.014) were found to be associated with decreased and increased risk of cervicitis respectively." (PMID 31365550, 2019). "TLR4 GCA and TLR9 GTA haplotypes were significantly associated with decreased and increased risk of cervicitis respectively." (PMID 31365550, 2019). "On the contrary, none of the genotypes or alleles of TLR9 rs5743844, rs352140, rs5743836 or rs352139 polymorphisms were associated with cervicitis." (PMID 31365550, 2019). "None of the other TLR9 haplotypes showed significant distribution between cases and controls as well as between TV positive and negative cases within the cervicitis patients." (PMID 31365550, 2019).
Chlamydia infection (3 papers, 2013 to 2019). "TLR9—as already mentioned, most of the studies assessing host genetic determinants of Chlamydia infections are focusing on the extracellular TLR2's and TLR4's contribution to the differences in the susceptibility and severity of the infection." (PMID 23781508, 2013). "During chlamydia infection TLRs found on immune cells particularly TLR2, TLR4 and TLR9 which are important in recognizing and sensing chlamydia, are highly expressed in the female genital tract where they mediate immune cell response to chlamydia." (PMID 31388084, 2019).
cognitive decline (3 papers, 2015 to 2024). "A recent study has indicated that TLR9 deficiency may exacerbate seizure-induced cognitive decline and recurrent seizure severity in mice." (PMID 28202935, 2017). "Furthermore, TLR9 deficiency exacerbated seizure-induced cognitive decline and recurrent seizure severity." (PMID 25751136, 2015). "Taken together, these results suggest that TLR9 signalling attenuates seizure-induced cognitive decline and recurrent seizure severity." (PMID 25751136, 2015). "Since seizure-induced aberrant neurogenesis is exacerbated in TLR9-KO mice, we examined whether KA-treated TLR9-KO mice show further cognitive decline by subjecting KA-treated or -untreated WT and TLR9-KO mice to a hippocampus-dependent place recognition task." (PMID 25751136, 2015).
congenital toxoplasmosis (3 papers, 2013 to 2017). Toxoplasma infection that is present from birth. "Our sequential analysis of other candidate susceptibility loci presented herein, found that TREX1, TIRAP MAL, FOXQ, and TLR9 also had allelic variants significantly associated with susceptibility to congenital toxoplasmosis in the NCCCTS (p < 0.05)." (PMID 28904337, 2017). "Taking into account all the analyzed SNPs, the multiple ACG variant at the TLR4 896 A>G, 1196 C>T, and TLR9 1635 G>A polymorphic sites was most common among the fetuses and newborns with congenital toxoplasmosis, with a prevalence rate of 52.8 %." (PMID 26254559, 2015). "The GTG multiple variants at the TLR4 and TLR9 SNPs were significantly less frequent among the fetuses and newborns with congenital toxoplasmosis than in the uninfected controls." (PMID 26254559, 2015). "The multiple SNP analysis indicated GTG variants at the TLR4 and TLR9 SNPs to be significantly less frequent in offspring with congenital toxoplasmosis than in uninfected offspring (p ≤ 0.0001)." (PMID 26254559, 2015). "In this article, we present reasons for the research of the plausible role of SNPs residing in TLR2, TLR4, and TLR9 genes in congenital toxoplasmosis development." (PMID 23161283, 2013). "TLR4 and TLR9 SNPs seem to be involved in protection against congenital toxoplasmosis." (PMID 26254559, 2015). "We suppose that genetic modifications, especially of TLR2, TLR4, and TLR9, might play a plausible role in congenital toxoplasmosis development." (PMID 23161283, 2013).
cryptosporidiosis (3 papers, 2014 to 2023). Intestinal infection with organisms of the genus Cryptosporidium. "Signaling TLR3 in combination with TLR5, TLR4 and TLR9 independently influence Cryptosporidium infection outcomes." (PMID 27467505, 2016).
cutaneous melanoma (3 papers, 2023 to 2025). A primary melanoma arising from atypical melanocytes in the skin. "Using an online analysis tool GEPIA 2, it was demonstrated that the OX40 expression was positively correlated with TLR9 and its downstream signaling pathway in the tumor microenvironment of skin cutaneous melanoma (SKCM)." (PMID 37700338, 2023).
deep vein thrombosis (3 papers, 2017 to 2022). "In a mouse model of deep vein thrombosis, toll-like receptor 9 was shown to play a role in thrombus resolution." (PMID 32027731, 2020). "TLR9 polymorphism was significantly associated with higher risk of VTE recurrence in female patients (HR 3.46, 95% CI 1.06–11.33) independent of acquired risk factors for VTE, family history, risk of thrombophilia and deep vein thrombosis (DVT) location." (PMID 28321710, 2017).
dermatitis (3 papers, 2015 to 2022). An inflammatory process affecting the skin. "In contrast to the renal phenotype, by 30 weeks of age few MRL/+ animals of either Tlr9 genotype had developed significant dermatitis (1 of 26 Tlr9+/+ and 5 of 26 Tlr9-/- animals with skin score > = 1)." (PMID 28278279, 2017).
endometriosis (3 papers, 2017 to 2025). The growth of functional endometrial tissue in anatomic sites outside the uterine body. "Additionally, the expression of CD19 + TLR9 in the comparisons of PE vs. CC (AUC = 0.86) and OE vs. CC (AUC = 0.92) may indicate that TLR9 on B lymphocytes is mainly associated with more advanced forms of endometriosis." (PMID 40862752, 2025). "Except for TLR9, all TLRs were found to be expressed (alone or co-expressed) in Tregs from endometriosis patients." (PMID 32236327, 2020). "Among CD4+ T cells, a markedly increased expression of all studied TLRs was observed in the endometriosis groups (p < 0.0001 for most comparisons), with the highest levels noted for TLR3 and TLR9." (PMID 40862752, 2025). "We observed markedly higher expression of TLR2, TLR3, TLR4, TLR7, TLR8, and TLR9 on CD4+, CD8+, and CD19+ lymphocytes in the endometriosis group, indicating their active participation in modulating immune responses in the disease setting." (PMID 40862752, 2025).
esophageal squamous cell carcinoma (3 papers, 2022 to 2025). Esophageal squamous cell carcinoma (ESCC) is a type of esophageal carcinoma (EC) that can affect any part of the esophagus, but is usually located in the upper or middle third. "Our previous studies have demonstrated that abnormal mitochondrial dynamics and biogenesis induce cytosolic mtDNA stress and promote the proliferation of HCC and esophageal squamous cell carcinoma (ESCC) cells by activating the TLR9 and/or cGAS-STING pathway." (PMID 40038250, 2025).
food allergy (3 papers, 2015 to 2019). Gastrointestinal disturbances, skin eruptions, or shock due to allergic reactions to allergens in food. "In various studies, therapeutic options including oral administration of IL-12, oral administration of a synthetic agonist of Toll-like receptor 9, or blockade of platelet-activating factor and histamine have been investigated for treatment of food allergy." (PMID 26793299, 2015).
Graves disease (3 papers, 2010 to 2023). Graves' disease is an autoimmune disorder that leads to overactivity of the thyroid gland (hyperthyroidism).It is caused by an abnormal immune system response that causes the thyroid gland to produce too much thyroid hormones. "In 2017, Cho’s team conducted polymorphism studies for TLR1–TLR6 and TLR9 genes to identify possible associations between the development of autoimmune thyroid disease (Hashimoto’s and Graves’ disease) and Korean children." (PMID 36982416, 2023). "The TLR9 −1486 T > C polymorphism (rs187084) has also been described to be significantly associated with increased susceptibility to ophthalmopathy in Taiwanese male patients with Graves’ disease." (PMID 28677621, 2017).
herpesvirus infection (3 papers, 2011 to 2024). "For example, the combination of TLR3 and TLR9 agonists has been shown to significantly reduce clinical signs of canine herpesvirus infection." (PMID 39355141, 2024). "CLPs from mice with active herpes infection are biased to DC differentiation in a largely TLR9 dependent manner." (PMID 21935459, 2011). "Of these, TLR3, TLR7, TLR8, and TLR9 contribute to antiviral immunity: TLR3 binds to double-stranded viral RNA; TLR7 and 8 detect single-stranded RNA viruses; and TLR9, which recognizes unmethylated cytosine-guanine (CpG) motifs in bacterial genomes, can also respond to herpesvirus infection." (PMID 33101294, 2020).
Hyperglycemia (3 papers, 2019 to 2025). An increased concentration of glucose in the blood. "Moreover, activation of Toll-like receptor 9 (TLR9) by hyperglycemia mediates oxidative stress and astrocytic dysfunction, leading to reduced TSP-1 secretion and synaptophysin expression." (PMID 34063474, 2021).
Immunodeficiency (3 papers, 2016 to 2018). Failure of the immune system to protect the body adequately from infection, due to the absence or insufficiency of some component process or substance. "Toll-like receptor 9 (TLR9) agonists have also been employed as adjuvants, helping to compensate for immunodeficiency such as that faced in late or early life." (PMID 26904695, 2016).
infectious mononucleosis (3 papers, 2020 to 2024). A condition characterized by an increase in mononuclear white blood cells and swollen lymph nodes, which is usually caused by infection with the Epstein-Barr virus. "Individuals with SNP at TLR4 896 A/G (rs4986790) and TLR9 1174 G/A (rs352139) had a higher risk of the infectious mononucleosis and clinical outcomes when compared with subjects with the wild-type genotype." (PMID 34578364, 2021). "Pie charts show the percentage distribution of the mononucleosis symptoms in patients with the TLR2 2029C/T and the TLR9 1174G/A SNPs." (PMID 32753695, 2020). "TLR-9 expression was upregulated in monocytes and B lymphocytes in children with chronic active Epstein–Barr virus infection (CAEBV) compared to those with infectious mononucleosis (IM)." (PMID 39201739, 2024).
intestinal inflammation (3 papers, 2011 to 2025). "This study demonstrates that TLR2, TLR4, TLR8, and TLR9 expression increases in active UC patients, and that the mRNA levels positively correlate with the severity of intestinal inflammation as well as with inflammatory cytokines." (PMID 22185629, 2011).
ischemic stroke (3 papers, 2015 to 2022). A stroke disorder caused by obstruction of blood flow to the brain, due to thrombotic (local blood clot formation) or embolic (due to a blood clot or other material traveling from another site) event. "Many of the identified genes, including TLR2, TLR3, TLR9, GRN, COL1A1, FN1, and LAMB1, were reported as upregulated genes in previous reports of ischemic stroke." (PMID 35887140, 2022).
keratitis (3 papers, 2010 to 2022). A corneal disease that is characterized by inflammation of the cornea. "Viral DNA differentially stimulated IL-6 and CCL2 through Tlr9 and cytoplasmic DNA sensors, respectively, but by itself, viral DNA was insufficient to induce keratitis." (PMID 20419141, 2010). "In the present study, we tested whether GLY protects the cornea against P. aeruginosa induced keratitis by blocking the HMGB1-TLR4 pathway exclusively or if TLR9 is involved." (PMID 36422579, 2022). "Furthermore, we show that the impact of pDCs in HSV-1 keratitis can be attributed to a TLR9-dependent secretion of IFN-α and preservation of Tregs in the draining lymph nodes (dLNs)." (PMID 32877681, 2020). "Furthermore, administration of a TLR9 antagonist was accompanied by elevated viral gB RNA in the cornea, confirming the critical role of TLR9 signaling in immune response during HSV-1 keratitis." (PMID 32877681, 2020). "In our studies, we demonstrated keratitis in Tlr9−/− mice similar to that in wild type mice." (PMID 20419141, 2010). "Because UV-inactivated virus induced keratitis to a similar degree as that induced by intact virus (Figs. 1and2), the possibility remained that viral CpG motifs and DNA in UV-inactivated virus might be activating Tlr9 in corneal cells." (PMID 20419141, 2010). "Although HSV-1 keratitis was accompanied by a considerable increase in corneal IFN-α levels, the increase was substantially inhibited by application of a TLR9 antagonist." (PMID 32877681, 2020). "Mice without toll-like receptor 9 (Tlr9) signaling developed clinical keratitis upon HAdV-37 infection similar to wild type mice, although the absolute numbers of activated monocytes in the cornea were less in Tlr9−/− mice." (PMID 20419141, 2010). "Taken together, the experiments with Tlr9−/− mice and DNA transfections confirm that viral genomic DNA contributes to cytokine expression and infiltration of mononuclear cells, but is not sufficient to induce clinical keratitis." (PMID 20419141, 2010).